IFNG (interferon gamma)
Diseases named in the same sentence as IFNG in open-access papers (continued):
Sharing a sentence is not in itself a finding about the gene and the disease.
Salmonella Infections (continued). "Cell fate-mapping experiments revealed that the majority of NKp46+T-bet+ILCs have a history of RORγt expression, suggesting that Salmonella infection can induce transdifferentiation of NKp46-ILC3s to IFNγ-producing ILC1s." (PMID 34938670, 2021). "We found that S. Infantis induces an increase in the proportion of proinflammatory CD4+ IFNγ+ T cells in Peyer’s patches in pigs; however, little is known regarding the roles of CD4+/− CCR6+/− T cells or CCR6+/− IFNγ+/− T cells during Salmonella infection." (PMID 32093767, 2020). "Interferon gamma promotes resistance mechanisms such as phagocytosis to help restrict intestinal and systemic Salmonella infection.Our results suggest that epithelial-intrinsic RAR signaling primes mucosal IFNγ production to restrict Salmonella infection." (PMID 32330185, 2020). "Our results in stopΔIEC mice demonstrated a direct correlation between intestinal IL-18 levels, RAR signaling, IFNγ production and resistance to Salmonella infection." (PMID 32330185, 2020). "Primary Salmonella infection increases interferon gamma (IFN-γ), tumor necrosis factor alpha (TNF-α), and interleukin 12 (IL-12) in circulation and in local tissues." (PMID 31540475, 2019). "Selected groups of macrophages were treated with 200 U/ml IFNγ 20 h before Salmonella infection, and where specified, some of the cultures were treated with 960 μM of the iNOS inhibitor L-NIL (Cayman Chemical, Ann Arbor, MI) at the time of infection." (PMID 29930310, 2018). "Sca-1 is an IFNγ-inducible activation marker on myeloid and lymphoid cells and it has been shown to be upregulated in Salmonella infections." (PMID 29973931, 2018). "Individuals with defects in the IL-12/IL-23 (IL-12β, IL-12Rβ1) and IFNγ (IFNγR1, IFNγR2, STAT1) pathways are in fact predisposed to Mendelian susceptibility to mycobacterial disease (MSMD) and/or disseminated Salmonella infection." (PMID 25268389, 2014). "The Th1 immune response with IFNγ as its central cytokine is generally considered as the most important for resistance to Salmonella infection and consistent with this, there were lower counts of S. Enteritidis in the spleens of vaccinated chickens." (PMID 22384225, 2012). "Additional support for an essential role for IFNγ in immunity to Salmonella comes from the mouse model of Salmonella infection." (PMID 21048923, 2010). "Blood levels of IFNγ increase both in Salmonella infections in mice and in humans, particular in the case of systemic disease." (PMID 21048923, 2010). "Using the mouse model of Salmonella infection, IFNγ production has been demonstrated in a variety of individual lymphocyte subsets." (PMID 21048923, 2010). "Human NK cells have also been shown to produce IFNγ in vitro in response to stimulation with Salmonella and to clear macrophages of Salmonella infection." (PMID 21048923, 2010). "Our findings indicate an inherent capacity of innate/innate-like lymphocyte subsets to produce IFNγ early in the response to Salmonella infection." (PMID 21048923, 2010). "NK cell numbers are elevated post infection with Salmonella and are an early source of IFNγ and mice depleted of NK cells show diminished resistance to Salmonella infection." (PMID 21048923, 2010). "This profile is in sharp contrast to the immune responses induced in Salmonella infection where microbial control is highly dependent on type 1 (Th1) immunity, mainly marked by the production of interferon-gamma (IFN-γ), tumor necrosis factor-alpha (TNF-α) and IL-1212,13." (PMID 38918457, 2024). "Lately, it was shown that NCR+ ILC3s may participate in host defense against Salmonella infection as ILC3s in the small intestine can convert their phenotype into IFNγ-producing ILC1s." (PMID 36838426, 2023). "Interferon-γ (IFNγ) is a key cytokine in defense against Salmonella infections." (PMID 37483638, 2023).
Salmonella Infections (continued). "Therefore, IFNγ-secreting ILCs seemingly act as double-edged sword in pathology during Salmonella infection, having both favorable and unfavorable effects." (PMID 36430676, 2022). "However, upon Salmonella infection, T-bet+ ILCs are the major producers of IFNγ, which triggers the secretion of mucus-forming gylcoproteins necessary for protection of the epithelial barrier." (PMID 36430676, 2022). "IL-12 is required for IFNγ production by ILCs after Salmonella infection." (PMID 34938670, 2021). "In summary, IFNγ-producing ILCs play a dual role in Salmonella infection." (PMID 34938670, 2021). "The immune responses following Salmonella infection in mice and humans have been reported as Th1-skewed phenotypes, which were a requisite for resolving infection of intracellular organisms via macrophage-activating cytokines such as IFNγ and TNFα." (PMID 33804435, 2021). "Altogether, these observations supported a critical role of Th1 cytokines in the defense against Salmonella infection, indicating that promoting IFNγ production in immunized mice was another serum factor relevant to the protection against Salmonella in this study." (PMID 33804435, 2021). "Additionally, serum Th1 or Th1-inducing cytokines such as IFNγ or IL12 were crucial to in vivo responses against Salmonella infection in view of their upregulation in human Salmonella infection, especially the systemic salmonellosis." (PMID 33804435, 2021). "However, on day 3 of Salmonella infection, stopΔIEC mice displayed a defect in interferon gamma production." (PMID 32330185, 2020). "γδ-T cells from patients with Salmonella infection produce high levels of IFNγ." (PMID 21048923, 2010). "Our finding in relation to IFNγ production by γδ-T cells in man suggests that the γδ-T cell subset may have an important role in protecting individuals from acute Salmonella infections." (PMID 21048923, 2010). "At the late stage of Salmonella infection, AvrA inhibits Interferon-gamma responses." (PMID 21182782, 2010). "Salmonella infection in chickens can cause mild enteric inflammation characterized by increased mRNA expression of proinflammatory cytokines including interleukin-6 (IL-6), IL-8, IL-12, LPS-induced tumor necrosis alpha factor (LITAF), and interferon gamma (IFN-γ)." (PMID 29706903, 2018). "Specifically, severe non-tuberculous mycobacteria or Salmonella infections in adults without any other known risk factors may warrant examination of autoantibodies against interferon-gamma because of their increasing recognition in the literature." (PMID 23336346, 2013). "IL-10 neutralisation in iron loaded Tim3−/− mice resulted in improved Salmonella infection control and restorage of CD4+ mediated IFNγ formation." (PMID 40939292, 2025). "Although NKp46+ ILCs are the main innate source of IFNγ production in the small intestine during Salmonella infection, accumulating data indicate that NCR− ILCs can also produce IFNγ under inflammatory settings." (PMID 36838426, 2023). "In summary, we found a prominent induction of ARG1 in macrophages upon Salmonella infection and an opposite regulation of ARG1 by IL-4 and IFNγ." (PMID 34359992, 2021). "Multiple immunomodulators and proinflammatory cytokines have protective roles against salmonella infections such as interleukins (IL)-1alpha, tumor necrosis factor (TNF) alpha, interferon gamma (IFN-γ), IL-12, IL-18, and IL-15." (PMID 33396722, 2020). "The induction of cytokines and immune relevant proteins such as IL1β, IL6, IL8, IL12, IL17, IL18, IL22, IL23, IFNγ, LITAF or iNOS following Salmonella infection of chickens have been reported repeatedly in many studies." (PMID 25475706, 2014). "Based on our previous observations, we were interested whether blocking of IL-10 could rescue the production of IFNγ in CD4+ T cells and therefore be beneficial for the control of the Salmonella infection in conditions of iron overload in Tim3−/− mice." (PMID 40939292, 2025).
Salmonella Infections (continued). "Individuals with inherited or acquired defects in TH1 immunity, such as those with IFNγ/IL12B/IFNγR1 polymorphisms or HIV/AIDS, are more susceptible to nontyphoidal Salmonella infections, but not to enteric fever." (PMID 38497655, 2024). "Salmonella infection can lead to mild intestinal inflammation, which releases cytokines and other factors like interleukin-6 (IL-6), IL-8, IL-12, LPS-induced tumor necrosis factor alpha (LITAF) and interferon gamma (IFN-γ)." (PMID 36311708, 2022). "The observed increase in the IL-1β and IFNγ mRNA of CD4+CD25- cells occurred only in the internal organ but not in the cecal tonsils, suggesting that the systemic host immune response to Salmonella infection differs from the mucosal immune response to Salmonella." (PMID 34843525, 2021). "Deletion of CASP4 or GSDMD did not alter bacterial invasion, but abrogated Salmonella-induced IFNγ-dependent cell death, confirming that Salmonella infection of HeLa cells activates the non-canonical inflammasome in an IFNγ-dependent manner." (PMID 32581219, 2020). "Our results suggest that LGG excludes pathogens and promotes mucosal immunity to Salmonella infection through expansion of CD4+ T-bet+ IFNγ+ T cells, elevation of T-bet levels, and activation of the IL-22BP–IL-22–STAT3 pathway." (PMID 28770173, 2017). "Cytokines such as tumor necrosis factor-alpha (TNF-α) and interferon-gamma (IFN-γ) produced by the cells of the innate immune system, such as dendritic cells, have antimicrobial activities and are also involved in control of Salmonella infection." (PMID 23989890, 2013). "Surprisingly, this clearance does not appear to involve IFNγ, since depletion of this cytokine from day 6 of Salmonella infection in the mouse does not prevent bacterial clearance." (PMID 21048923, 2010). "Studies in the mouse indicate that αβ-T cells are not required during the first week of Salmonella infection and IFNγ is produced in response to IL12 and IL18 in rag−/− and SCID mice that lack T cells." (PMID 21048923, 2010). "IFNG, GBP4, and GBP5 showed dramatic increase post Salmonella infection." (PMID 21172007, 2010). "In the Salmonella infection model, the quantity of dietary iron did not affect the expression of TIM-3, IFNγ, or IL-10 on CD8+ T cells." (PMID 40939292, 2025). "This does not mean that these cells do not respond to Salmonella infection as IL17, IL22 or IFNγ expressed by T-lymphocytes are induced within the range of 10 to 100 fold." (PMID 25475706, 2014).
liver fibrosis (135 papers, 2011 to 2025). "The latest correlation could demonstrate a pathogenic role of IFNγ in fibrogenesis or, on the contrary, a physiological response in the attempt to reverse the development of liver fibrosis." (PMID 36768637, 2023). "Herein, promising therapeutic approaches were aroused, such as the TNFα/TNFR1 axis blockage to prevent NAFLD progression, anti-TGF-β therapy to alleviate liver fibrosis or neutralization of IFNγ activity to revert both liver inflammation and injury." (PMID 36768637, 2023). "In the liver, mRNA expression of the most common isoform of TGF-β (TGF-β1) was increased in a murine model prone to develop liver fibrosis (obese IFNγ-/- subjected to a high-fat diet)." (PMID 36768637, 2023). "Triggering IL6/STAT3 signaling enhances HSC activation and liver fibrosis, while IFNγ/STAT1 signaling exhibits opposite effects." (PMID 37860111, 2023). "While IFNγ contributes to liver injury and inflammation, this cytokine also exerts a protective effect against liver fibrosis, through the STAT1 signaling pathway." (PMID 36768637, 2023). "Despite these findings, evidence was provided from diet-induced murine NASH models indicating that IFNγ- or Stimulator of interferon genes (STING)-deficiency attenuates steatosis and liver fibrosis, as well as TNFα and IL-6 mRNA liver expression." (PMID 36768637, 2023). "Gene Set Enrichment Analysis (GSEA) showed an enrichment of pathways associated with inflammation and liver fibrosis in SuHx animals, in particular TNFα signaling, IL6-JAK-STAT3 signaling, Interferon alpha (IFNα) and gamma (IFNγ) response." (PMID 35369312, 2022). "Among these hub genes, some are cytokines and chemokines closely related to liver fibrosis (IFNG, CCL3, CCL4, CCL5, and CXCR4)." (PMID 35903097, 2022). "The anti-fibrotic effects of interferon-gamma (IFN-γ) are well established in hepatic fibrosis models." (PMID 31006829, 2019). "This was demonstrated by the amelioration of liver fibrosis in vivo, after activation of NK cells by poly I:C or treatment of rodents with IFNγ." (PMID 26501061, 2015). "Emerging evidence suggests that NK cells and IFNγ are very important in the negative regulation of liver fibrosis." (PMID 26501061, 2015). "NK cells and NKT reduce liver fibrosis by producing interferon gamma (IFN-γ) and inducing death of early or senescence of activated HSCs." (PMID 25954568, 2015). "Similar to pPB-PEG-IFNγ, Fibroferon markedly inhibited both early and advanced CCl4-induced liver fibrosis in mice and significantly reduced IFNγ-related side effects." (PMID 26501061, 2015). "In the present study, we assessed the intracellular activation of the pSTAT1α signaling pathway after 24 h of IFNγ, mimIFNγ, BiPPB-IFNγ and BiPPB-mimIFNγ administration in CCl4-induced liver fibrosis in mice." (PMID 24587093, 2014). "Among the potent anti-fibrotic therapeutic cytokines, Interferon gamma (IFNγ) is shown to be highly efficacious in vitro and in vivo in liver fibrosis models, but it failed in clinical trials due to reduced efficacy and unwanted systemic effects." (PMID 24587093, 2014). "For instance, PPARγ ligands, interferon gamma (IFNγ), and antioxidants reduce liver fibrosis by inhibiting TGF-β1 expression and therefore HSC activation." (PMID 25606051, 2014). "IFNγ (Interferon gamma-1b) has also been explored in clinical trials in patients suffering from liver fibrosis, renal fibrosis or idiopathic pulmonary fibrosis." (PMID 24587093, 2014). "Accordingly, the depletion of IFNγ in obese mice accelerated the development of liver fibrosis." (PMID 36768637, 2023). "Mechanistically, we showed that accumulation of liver fibrosis-related cytokines, including TGFβ, IFNγ, TNFα, etc, could induce UC-MSC senescence and SASP through activation of JAK/STAT3 signaling pathway." (PMID 37507381, 2023).
liver fibrosis (continued). "IFNγ, a type II interferon with important immunomodulatory properties, triggers the transactivation of many inflammatory-related genes, contributing to the pathogenesis of schistosome-induced hepatic fibrosis." (PMID 36148947, 2022). "Overexpression of interferon gamma via AAV has been shown to suppress markers of hepatic fibrosis, where changes in hepatic lipidome could offer a mechanistic link." (PMID 33417276, 2021). "Chronic alcohol consumption accelerates liver fibrosis in patients with viral hepatitis, which might be due to the suppression of anti-fibrotic property of NK cells and interferon-gamma (IFN-γ)." (PMID 31244862, 2019). "We next examined whether IFNγ or IL-17 is responsible for the development of liver fibrosis by comparing the degree of liver fibrosis upon in vivo blockade of IFNγ and IL-17A in WT and TCRδ−/− mice mice." (PMID 30930903, 2019). "In addition, FZHY has also enhanced the activation of hepatic NK cells and the production of interferon-gamma (IFN-γ) effectively against liver fibrosis." (PMID 26221168, 2015). "In addition to the demonstrated antifibrotic properties of redirected truncated IFNγ in a mouse liver fibrosis model, antifibrotic effects of pPB-PEG-IFNγ were also found in the unilateral ureteral obstruction (UUO) mouse model for renal fibrosis." (PMID 26501061, 2015). "Since, activated HSC express high-level of platelet derived growth factor beta receptor (PDGFβR), we investigated the potential of PDGFβR-specific targeting of IFNγ and its signaling peptide that lacks IFNγR binding site (mimetic IFNγ or mimIFNγ) in liver fibrosis." (PMID 24587093, 2014). "Similarly, administration of IFNγ reduced fibrosis in rat models of hepatic fibrosis, and long-term administration of IFNγ reduced fibrosis in patients with chronic Hepatitis B infections." (PMID 23653658, 2013). "Given the complex role of IFNγ (see Section 5.3), this observation could be the consequence of a failure of this protective mechanism, contributing to a proinflammatory milieu, or a protective mechanism against liver fibrosis in these patients." (PMID 36768637, 2023). "In mice with CCl4-induced liver fibrosis, we induced spontaneous resolution by cessation of CCl4 for one week after four weeks of CCl4 treatments and we induced resolution by treatment with the antifibrotic cytokine IFNγ in the last two weeks of eight weeks of CCl4 treatments." (PMID 32455750, 2020). "In response, NK-T cells can produce pro-inflammatory cytokines such as interferon-gamma (IFN-γ) to modulate the function of KCs, influencing the progression of liver fibrosis." (PMID 39635524, 2024). "We investigated the changes in cytokines, interferon gamma (IFN-γ), tumor necrosis factor-α (TNF-α), and interleukin 6 (IL-6) along with aspartate aminotransferase (AST), alanine aminotransferase (ALT) level, and hepatic fibrosis in three regimens." (PMID 35889747, 2022). "Further in vivo experiments validated the significant mitigatory effects of SNS on inflammatory infiltration and pro-inflammatory cytokine contents (IFNγ, IL-1β and TGF-β1) in liver tissues of mice with liver fibrosis." (PMID 34276360, 2021). "Additionally, in advanced liver fibrosis, activated HSCs produce TGF-β, which can suppress NK cell antifibrotic functions, such as degranulation and interferon-gamma (IFN-γ) production, thereby promoting the progression of liver fibrosis." (PMID 40607394, 2025). "Interestingly, interferon gamma (IFN-γ) increased but TNF-α, interleukin 6 (IL-6), hepatic fibrosis, and steatosis decreased in the add-on groups." (PMID 35889747, 2022). "Systemic administration of interferon gamma (IFN-γ) also has some unwanted effects, yet a fusion protein of IFN-γ and PDGFβR bicyclic peptide was shown to inhibit liver fibrosis in vivo, although a low bioavailability was an important drawback in this intervention." (PMID 34055744, 2021).
liver fibrosis (continued). "Recently, we have shown that using PDGFβR-specific delivery of IFNγ to activated HSC; acute and advanced liver fibrosis in vivo could be significantly inhibited with minimal adverse effects." (PMID 24587093, 2014). "In the present study, we have directed IFNγ or mimetic IFNγ (signaling moiety of IFNγ lacking extracellular IFNγR binding site while retaining activities of IFNγ) to PDGFβR-expressing activated HSC using bicyclic PDGFβR peptides to inhibit liver fibrosis with reduced adverse effects." (PMID 24587093, 2014). "Both baseline increased expression of IFNγ and IL2 and subsequent decrement after SVR were observed irrespective of HCV genotype or liver fibrosis measured by transient elastography." (PMID 33917265, 2021).